SQLE (squalene epoxidase)
Diseases named in the same sentence as SQLE in open-access papers (continued):
Sharing a sentence is not in itself a finding about the gene and the disease.
tumor (64 papers, 2008 to 2025). "The expression levels of genes ESRP1, GRHL2, MTHFD2, RACGAP1, and SQLE, considered risk factors, were significantly up‐regulated in tumor tissues compared with normal tissues and were statistically significantly associated with a poor prognosis." (PMID 40586163, 2025). "Squalene epoxidase (SQLE) is a key enzyme in cholesterol biosynthesis and has been shown to negatively affect tumor immunity and is associated with poor outcomes of immunotherapy in various cancers." (PMID 39763673, 2024). "For example, squalene epoxidase (SQLE), one of the rate-limiting enzymes in cholesterol synthesis, has been linked to tumor development and has been investigated as a potential therapeutic target." (PMID 38062450, 2023). "Our findings reveal that SQLE is overexpressed in cisplatin‐resistant tumors and its loss restore tumor sensitivity to cisplatin, implicating SQLE as a promising anticancer therapeutic target for cisplatin‐resistant HNSCC." (PMID 37490552, 2023). "The SQLE gene encodes squalene epoxidase to catalyze the oxidation of squalene that could change the lipid profile of tumor cells and protect them from ferroptosis." (PMID 34900981, 2021). "For the dangerous markers, the SQLE gene encodes squalene epoxidase to catalyze the oxidation of squalene that could change the lipid profile of tumor cells and protect them from ferroptosis, and the inhibition of the flavoprotein SQLE with NB‐598 could enhance ferroptosis." (PMID 37461802, 2023). "The inhibition of this enzyme, when combined with squalene epoxidase inhibition, resulted in a more pronounced suppressive effect on cell proliferation and tumor growth compared with single inhibition." (PMID 40052996, 2025). "The downregulation of lipid metabolism-related genes like CYP17A1 and SQLE suggests the core reconfigures its metabolic pathways to support aggressive tumor behavior, focusing more on structural adaptation and motility." (PMID 40431665, 2025). "Squalene epoxidase (SQLE), the second rate-limiting enzyme in cholesterol synthesis, plays an important role in cholesterol synthesis and alters the gut microbiota and tumor immunity." (PMID 39588004, 2024). "SQLE-mediated cholesterol homeostasis participated in tumor growth through various factors, mainly increased tumorigenicity and metastasis of cancers." (PMID 39617776, 2024). "Squalene epoxidase (SQLE) is capable of promoting tumor growth by inhibiting apoptosis and is able to interact with the TGFb-SMAD axis to promote EMT and metastatic capacity." (PMID 38927057, 2024). "As a key enzyme in cholesterol synthesis, SQLE activity determines the abundance of cholesterol and cholesterol derivatives, which promotes tumor growth through the accumulation of cholesterol/cholesterol esters and, subsequently, multiple oncogenic pathways." (PMID 39588004, 2024). "SQLE expression was upregulated in pancreatic adenocarcinoma tumor tissues compared to normal tissues, and it predicted poor DFS and OS in cancer patients; amplification was the dominant type of mutation and was closely associated with OS, DFS, and PFS." (PMID 38612682, 2024). "SQLE also acts either as a tumor suppressor or a tumor activator according to different cell types or cellular localization." (PMID 35962621, 2022). "The conclusion of the research was that squalene epoxidase inhibitors are novel tumor-specific radiosensitizers that promote ER stress and suppress homologous recombination, providing a novel potential therapeutic approach to improve radiotherapy efficacy." (PMID 35885460, 2022). "Amplification of 8q24.11-13 (THRAP6, DCC1, SQLE, SPG8) and 11q14.1 (NDUFC2, ALG8, USP35) have been associated with poor prognosis in a novel subtype of high-grade ER- tumors." (PMID 20932292, 2010). "Squalene epoxidase mRNA was detected in all 160 tumour tissues, with the tumour with the highest expression displaying a 290-fold higher level of SQLE mRNA than the lowest." (PMID 18728668, 2008).
tumor (continued). "Furthermore, reported in various cancers except for EAC as relevant to activating PI3K-Akt signaling pathway or promoting tumor through SENP3/SP1/SQLE axis, SERPINH1 was also identified as a key gene in EAC in the current study." (PMID 40872572, 2025). "SQLE is highly expressed in multiple types of cancer cells and promotes tumor progression." (PMID 39588004, 2024). "SQLE is the second rate-limiting enzyme of cholesterol synthesis and plays an important role in cholesterol synthesis, alteration of the intestinal gut microbiota, and tumor immunity." (PMID 39588004, 2024). "Studies have identified squalene epoxidase (SQLE) as a key regulator of various physiological processes, including cholesterol biosynthesis, modulation of the gut microbiota, and the regulation of tumor immunity." (PMID 39588004, 2024). "Interestingly, the aerobic exercise training inhibited the squalene epoxidase, an enzyme involved in the reprogramming of cholesterol metabolism notably correlated with immuno-cold tumor microenvironment." (PMID 39555455, 2024). "EDIL3, known for its involvement in endothelial cell adhesion, may facilitate tumor angiogenesis, while SQLE, an enzyme in the cholesterol biosynthesis pathway, could support membrane biogenesis in rapidly proliferating tumor cells." (PMID 39015570, 2024). "Furthermore, we observed that ENO1, PFKFB3, NSDHL and SQLE were highly expressed in recurrent HNSCC tumor compared with first diagnosed HNSCC patients surviving at least 5 years." (PMID 36841765, 2023). "In contrast, FANCD2, PTGS2, SLC2A1, and SQLE were higher in tumor compared to normal tissues." (PMID 36733386, 2022). "Furthermore, lower expression levels of SCD, SQLE, FADS2 and TFRC were significantly associated with increased tumor infiltration of DCs and/or B cells." (PMID 35818395, 2022). "In addition, our previous study found that squalene epoxidase, an essential gene to regulate immune escape in tumor cells by modulating cholesterol biosynthesis, could be down-regulated by physical exercise." (PMID 39845707, 2025). "Furthermore, ferroptosis-related genes with copy number amplification (including FADS2, NQO1, ABCC1, ACSF2, HMOX1, FANCD2 and SQLE) demonstrated higher expression in tumour tissues, and those with copy number deletion (including CRYAB, ACSL3, ZEB1) demonstrated lower expression in tumour tissues." (PMID 35145965, 2022). "CagA also enhances programmed death ligand-1 (PD-L1) stability by up-regulating the expression of squalene epoxidase (SQLE) and inhibits T cell activation and anti-tumor immune responses." (PMID 40432137, 2025). "Squalene epoxidase (SQLE), a rate-limiting enzyme in cholesterol biosynthesis, drives cholesterol accumulation, which not only impairs the effector function of tumor-infiltrating CD8+ T cells but also promotes MDSC activation." (PMID 40051497, 2025). "SQLE overexpression reduced squalene, increased lipid ROS, and enhanced ALK+ ALCL cell sensitivity to GPX4 inhibitors (ML162, RSL3), inhibiting tumor growth." (PMID 40145543, 2025). "Our data showed that both ENO1, PFKFB3, NSDHL and SQLE have high expression levels in clinical HNSCC samples, and all of them presented higher expression in patient with recurrence tumor." (PMID 36841765, 2023). "Utilizing multiple tumor models and examining an internal HNSCC cohort, squalene epoxidase (SQLE) is pinpointed as a key driver of chemoresistance and tumorigenesis, operating through a cholesterol‐dependent pathway." (PMID 37490552, 2023). "Squalene synthase (SQS) and squalene epoxidase (SQLE) also affect the synthesis of cholesterol and tumor immune response." (PMID 37064872, 2023).
tumor (continued). "Through transcriptional upregulation of SQLE, a rate-limiting enzyme in cholesterol synthesis pathway, MYC increases cholesterol production and promotes tumor cell growth." (PMID 33791309, 2021). "In summary, three genes (ACACA, SQLE, and PHKG2) in the newly developed signature have established roles in the protection of tumor cells against ferroptosis, whereas TFRC has the opposite effect." (PMID 33989111, 2021). "Consistent with the rate decrease, tumor mRNA and protein expression of HMGCS1, MVK, MVD, and SQLE was also significantly downregulated by XY018 or its combination with statin." (PMID 31604910, 2019). "Differential expression of seven of these genes (CFD, ALDH18A1, CHKA, DDIT3, ITGA6, PSPH and SQLE) was replicated in another set of 12 paired NASH-HCCs and adjacent non-tumor livers by RT-qPCR (all P < 0.05 by paired t test)." (PMID 30367044, 2018). "Genes involved in glycolysis (ALDOA, LDHA, PGK1, PFKL, PGM1) and other metabolic processes (GPX4, PRDX4, ACO2, ASPH, IDH2, SQLE, NPC2, SPTSSA) were upregulated in primary tumor cells, suggesting that the metabolism in primary tumors was distinct from that in their matched metastasis." (PMID 39225101, 2024). "SQLE protein was mainly expressed in the cytoplasm and nucleus of STAD tissues, while a small amount was expressed in the cytoplasm and nucleus of adjacent non-tumor tissues." (PMID 36808302, 2023). "Given that morphological plasticity is a key determinant of cell migration, many of the identified genes were found to have a role in promotion of tumor cell migration and invasion, including ECM production and mesenchymal state induction (HEG1, BZW2, DCAF13, SQLE, PKIA)." (PMID 35879361, 2023). "To demonstrate increased activity of the MVA pathway in CSCs of CRC, we cultured tumor spheres and found significantly elevated protein and mRNA levels of key enzymes of the MVA pathway, including HMGCR, FDPS, GGPS1, and SQLE, in tumor spheroids compared to 2D adherent cultured cells." (PMID 32911743, 2020). "Notably, among the top-ranked CTD-suppressed genes, we found that five genes, including TOP2A, ACSL4, SQLE, CDK4, and SLC6A14 were significantly elevated in HCC clinical specimens, suggesting that NCTD targets to inhibit the expression of these genes to exert anti-tumor effects in HCC." (PMID 40271060, 2025).
cancer (59 papers, 2011 to 2025). A tumor composed of atypical neoplastic, often pleomorphic cells that invade other tissues. "SQLE catalyzes a critical step in cholesterol biosynthesis and is strongly associated with chemoresistance and poor prognosis in cancers, including osteosarcoma." (PMID 40370434, 2025). "Aberrant activity of squalene monooxygenase (SM, also known as squalene epoxidase), the rate-limiting enzyme of the committed cholesterol synthesis pathway, is accordingly implicated in a growing list of cancers." (PMID 38537696, 2024). "Key enzymes, including HMGCR (3-hydroxy-3-methylglutaryl-CoA reductase) and squalene monooxygenase (SQLE), play central roles in maintaining cholesterol homeostasis and supporting cancer cell proliferation." (PMID 40370434, 2025). "The TRB’s cytotoxic effect on cancer cells was attributed to its ability to block the squalene epoxidase enzyme." (PMID 40732261, 2025). "SQLE has previously been identified as a metabolic oncogene that enhances cancer proliferation and invasion across various cancer types." (PMID 41005980, 2025). "The emerging role of cholesterol metabolism in cancer progression has opened new avenues for research, particularly focusing on squalene epoxidase (SQLE)." (PMID 39654652, 2024). "As the second rate-limiting enzyme in cholesterol biosynthesis, SQLE is a fascinating enzyme that plays a vital role in human cancers." (PMID 38612682, 2024). "SQLE is overexpressed in several cancers and the high expression of SQLE is closely related to the poor prognosis of cancer patients, including CRC." (PMID 38762737, 2024). "Studies have demonstrated that squalene epoxidase (SQLE), as a key rate-limiting enzyme in cholesterol biosynthesis, is involved in cancer development." (PMID 37770925, 2023). "Beyond that, miRNAs usually exert their biological role via interacting with target genes, and Squalene epoxidase (SQLE) performed as a pro-cancer factor, which can promote cell proliferation in NPC." (PMID 37554147, 2023). "The results showed that ENO1, PFKFB3, NSDHL and SQLE were primarily detected in the in the cytoplasm of cancer cells in HNSCC tissues and the expression of these protein in recurrent HNSCC was significantly higher than that in normal tissues." (PMID 36841765, 2023). "Compared with normal tissues, the expression of FRGs with higher amplification frequency increased significantly in cancer tissues (e.g., SQLE, NFS1, and ACACA), and vice versa (e.g., GOT1, HMGCR, and FTH1)." (PMID 35444656, 2022). "Recently, increasing attention has been paid to the role of Squalene epoxidase (SQLE) in several types of cancers." (PMID 35813482, 2022). "Taken together, we demonstrate that SQLE expression is upregulated in multiple types of human cancer (including PAAD) and negatively correlated with the prognosis of PAAD." (PMID 35720314, 2022). "Upregulation of the metabolic genes (ALDH18A1, CAD, CHKA, POLD4, PSPH, and SQLE) and aberrant expression of cancer-related genes (ALCAM, ITGA6, DDIT3, MAP3K6, and PAK1) were found in mouse fed with high-fat-high-cholesterol similar to human NASH-HCCs." (PMID 31795276, 2019). "It was previously discovered that squalene epoxidase can reduce cell apoptosis and accelerate the cell cycle advancement in cancer cells, while inhibition of this enzyme might halt the cancer cells’ progression." (PMID 40732261, 2025). "Moreover, inhibition of specific enzymes involved in cholesterol metabolism, including lanosterol synthase (LSS), farnesyl diphosphate synthase (FDPS), and squalene epoxidase (SQLE), has been shown to suppress cancer metastasis." (PMID 38762737, 2024). "SQLE has been reported to act as an oncogene in various cancers." (PMID 39588004, 2024).
cancer (continued). "Squalene epoxidase (SQLE), a second rate‐limiting enzyme in cholesterol biosynthesis, has been reported as a bona fide oncogene in several cancers, including breast and liver." (PMID 38517197, 2024). "This prompted us to wonder whether the inhibition of SQLE, another rate-limiting enzyme downstream in cholesterol biosynthesis, is able to generate survival benefits in cancer patients while overcoming these side effects." (PMID 38612682, 2024). "SQLE overexpression induced significant changes in cholesterol metabolism, biosynthesis of amino acids, protein digestion and absorption, central carbon metabolism in cancer, biosynthesis of plant secondary metabolites, and glutathione metabolism pathways." (PMID 39617776, 2024). "ATP-citrate lyase (ACLY), acetyl-CoA carboxylase (ACC), fatty acid synthase (FASN), stearoyl-CoA desaturase-1 (SCD1), 3-hydroxy-3-methyl-glutaryl-CoA reductase (HMGCR), and squalene epoxidase (SQLE) are overexpressed in cancer cells and are under the transcriptional control of the AR." (PMID 36674430, 2023). "Besides these antioxidant activities, GA derivatives have been reported to induce apoptosis in cancer cells, scavenge free radicals, signal pathway interference involving oxygen free radicals and Ca2+, as well as squalene epoxidase inhibition." (PMID 35626946, 2022). "Additionally, enzymes such as squalene epoxidase (SQLE) and sterol O-acyltransferase 1 (SOAT1) play significant roles in cholesterol biosynthesis and esterification, respectively, and their dysregulation has been associated with cancer progression." (PMID 40707931, 2025). "Moreover, SQLE was identified as a crucial cancer-promoting gene in BC." (PMID 34715817, 2021). "Accumulating evidence suggests that squalene epoxidase (SQLE) plays a pivotal role in the development and progression of several cancer types in humans." (PMID 35720314, 2022). "Our study indicates upregulation of multiple genes that are particularly enzymes involved in cholesterol biosynthesis, i.e., GGPS1, SQLE, FDPS, HMGCS1, and HMGCR, which were also reported in distinct cancer models." (PMID 35050168, 2022). "Numerous studies have reported that ZEB1 contributes to cancer progression, while the role of CRYAB and SQLE in BC is rarely reported." (PMID 34490263, 2021). "Disrupting the expression of key enzymes in cholesterol biosynthesis, such as HMGCR and SQLE, appears to prevent carcinogenesis mechanisms in colorectal, breast, prostate and NAFLD-HCC cancers." (PMID 32712598, 2020). "Squalene epoxidase (SQLE) is a key enzyme in cholesterol biosynthesis and is a target for hypercholesteremia and cancer drug development." (PMID 30626872, 2019). "Recently, the aberrant expression of SQLE, which is responsible for epithelial to mesenchymal transition (EMT), has been reported in various types of cancer." (PMID 31072053, 2019). "We demonstrated for the first time the aberrant expression of cancer-related genes (ALCAM, ITGA6, DDIT3, MAP3K6 and PAK1) and metabolism-related genes (ALDH18A1, CAD, CHKA, POLD4, PSPH, SQLE and CFD) in human NASH-HCCs." (PMID 30367044, 2018). "Twenty of these genes are located in 8q22–q24 and 17q21, including PAPBC1, RAD21, ATAD2, MTSS1, SQLE, ST3GAL1, C17orf37, ABCC3 and PTPN2, previously reported as cancer-related genes." (PMID 21339811, 2011). "The key enzymes in cholesterol synthesis include 3-hydroxy-3-methylglutaryl-coenzyme A reductase (HMGCR) and SQLE, and previous studies suggest that the inhibition of HMGCR could enhance the efficacy of cancer treatments." (PMID 38762737, 2024). "In addition, some new cholesterol metabolism molecules, such as SOAT1, SQLE and NPC1, have recently become promising drug targets for cancer treatment." (PMID 38817876, 2024).
cancer (continued). "ALB and SQLE were upregulated in the “amino acid metabolism, increased albumin levels, and molecular transport” network at all time points, and actin-related protein 3B (ACTR3B) was upregulated in the “cancer, hematological disease, and immunological disease” network at all time points." (PMID 36299731, 2022). "The results showed that apart from EPAS1 and RAD51AP1 that without immunohistochemistry data, SQLE, CAPG, RRM2, SLC1A5, and SRC as dangerous genes were higher expressed in cancer tissues." (PMID 37461802, 2023).
infection (4 papers, 2012 to 2022). The state of being infected such as from the introduction of a foreign agent such as serum, vaccine, antigenic substance or organism. "Microarray data showed that transcription of two genes of the cholesterol biosynthesis pathway, HMG-CoA reductase and squalene epoxidase was increased by infection." (PMID 22928052, 2012).